WIPF2 (WAS/WASL interacting protein family member 2)
Description:
Plays an active role in the formation of cell surface protrusions downstream of activated PDGFB receptors. Plays an important role in actin-microspike formation through cooperation with WASL. May cooperate with WASP and WASL to induce mobilization and reorganization of the actin filament system.
Synonyms: WICH; WIRE
Tractability: PROTAC: its protein half-life has been measured.
Gene: Protein-coding gene on chromosome 17 (40,218,743 to 40,284,136, forward strand). Ensembl gene ENSG00000171475.
Subcellular location: Cytoplasm, cytoskeleton
Pathways (Reactome):
Signal Transduction: CDC42 GTPase cycle; RAC1 GTPase cycle; RHO GTPases Activate WASPs and WAVEs; RHOJ GTPase cycle
Disease: FCGR3A-mediated phagocytosis
Immune System: Regulation of actin dynamics for phagocytic cup formation
Gene Ontology:
Molecular function: protein binding; actin binding
Cellular component: cytosol; cytoskeleton
Genetic constraint (gnomAD): Loss-of-function variants: 14 observed, 28.14 expected, observed/expected ratio (o/e) 0.5, 90% interval 0.33 to 0.78. The upper end of that interval is the gene's LOEUF score, 0.78, which puts it in group 3 of 6, group 1 being the genes least tolerant of losing a copy. Missense variants: 496 observed, 528.7 expected, observed/expected ratio (o/e) 0.94, 90% interval 0.87 to 1.01. Synonymous variants: 188 observed, 203.63 expected, observed/expected ratio (o/e) 0.92, 90% interval 0.82 to 1.04.
Homologues: Orthologues: chimpanzee WIPF2 (99% identical), macaque WIPF2 (99% identical), dog WIPF2 (97% identical), pig WIPF2 (96% identical), mouse Wipf2 (94% identical), rat Wipf2 (94% identical), guinea pig WIPF2 (89% identical), zebrafish wipf2b (67% identical), zebrafish wipf2a (54% identical). Paralogues in human: WIPF1 (45% identical), WIPF3 (38% identical).
Diseases named in the same sentence as WIPF2 in open-access papers:
WIPF2 is named in the same sentence as 7 diseases in open-access papers, as found by Europe PMC text mining. Sharing a sentence is not in itself a finding about the gene and the disease. The quoted sentences say what the papers report.
breast carcinoma (2 papers, 2013 to 2016). "The screens were done in metastatic breast cancer cells expressing vimentin at high levels and three novel vimentin regulators - WAS/WASL interacting protein family member 2 (WIPF2), methylenetetrahydrofolate dehydrogenase 2 (MTHFD2) and ephrin type-B receptor 4 (EPHB4) were identified." (PMID 23295955, 2013).
hepatocellular carcinoma (1 paper, 2024). A malignant tumor that arises from hepatocytes. "Moreover, Wipf2 is involved in competing for endogenous RNA (ceRNA) modes and promotes tumor development in hepatocellular carcinoma." (PMID 38596793, 2024).
cancer (3 papers, 2013 to 2025). A tumor composed of atypical neoplastic, often pleomorphic cells that invade other tissues. "This study identifies WIPF2, EPHB4 and MTHFD2 as novel regulators of vimentin expression by using a high-throughput RNAi screening approach targeting cancer relevant genes." (PMID 23295955, 2013).
tumor (3 papers, 2016 to 2025). "We further investigated contexts of these spMOCA’s hub genes, where we identified specific prognostic genes serves as hub genes in the same tumor type, for example, WIPF2 and CASC3 for BRCA, COX6A1 and PRAP1 for CRC, E2F1 and AKR1C3 for LUSC, and TSPAN3 and SLC4A11 for OVCA." (PMID 41370198, 2025).
infection (2 papers, 2016 to 2019). The state of being infected such as from the introduction of a foreign agent such as serum, vaccine, antigenic substance or organism. "Localization of WIPF2 fluorescent signal with GFP signal from the conidia was observed to be localized as a “ring” around the conidia 15 min post-infection." (PMID 30792969, 2019). "Furthermore, 60 min post-infection the WIPF2 signal was observed to be diffused throughout the cells." (PMID 30792969, 2019).
WIPF2 also shares sentences with these, for which no sentence is quoted: metastatic cancer (1 paper); Williams syndrome (1).